HNRNPA2B1 (heterogeneous nuclear ribonucleoprotein A2/B1)
Diseases named in the same sentence as HNRNPA2B1 in open-access papers (continued):
Sharing a sentence is not in itself a finding about the gene and the disease.
esophageal cancer (19 papers, 2016 to 2024). A primary or metastatic malignant neoplasm involving the esophagus. "Higher HNRNPA2B1 gene expression was found to be associated with LN metastasis in esophageal carcinoma." (PMID 37142981, 2023). "On the other hand, the finding regarding HNRNPA2B1 is contrary to other studies where high expression of HNRNPA2B1 was significantly associated with poor prognosis in osteosarcoma, esophageal cancer and adrenocortical carcinoma." (PMID 36189296, 2022). "In esophageal cancer, the m6A reader HNRNPA2B1 promotes the expression of ACLY and ACC1, which increases lipid accumulation." (PMID 38560499, 2024). "Omics research shows that HNRNPA2B1 is substantially increased in esophageal cancer (ESCA) and the prognosis is worse in patients with a high level of HNRNPA2B1." (PMID 37055798, 2023). "HNRNPA2B1 can promote the progression of esophageal cancer by up-regulating fatty acid synthase as a carcinogen." (PMID 37074800, 2023). "For example, there is a significant positive correlation between HNRNPA2B1 and M1 macrophages in esophageal cancer, and the expression of HNRNPA2B1 is higher in M1 macrophages and T/NK cells than in other cells in glioblastoma." (PMID 36189296, 2022). "We found that the significantly positive correlation between HNRNPA2B1 and miR-17/miR-18a/miR-106b in 14 paired esophagus cancer tissues and tumor-adjacent tissues." (PMID 34277606, 2021). "Recently, HNRNPA2B1 was shown to function as an oncogenic factor in promoting esophageal cancer progression by the up-regulation of fatty acid synthesis enzymes ACLY and ACC1." (PMID 34395102, 2021). "We observed a pronounced upregulation of hnRNPA2B1 in various TCGA‐gastrointestinal tumor datasets, encompassing esophageal carcinoma (ESCA, p < 0.001), stomach adenocarcinoma (STAD, p < 0.001), colon adenocarcinoma (COAD, p < 0.001), and rectum adenocarcinoma (READ, p < 0.05)." (PMID 38887155, 2024). "The miR-17-92 cluster is a classic miRNA family that has been reported to participate in cancer chemoresistance, for example, RNA-binding protein heterogeneous nuclear ribonucleoprotein A2/B1 (HNRNPA2B1) may affect the prognosis of esophageal cancer by regulating the miR-17-92 cluster." (PMID 36810285, 2023). "Moreover, m6A regulator HNRNPA2B1 was found to function as an oncogenic factor to accelerate esophageal cancer (ESCA) progression, and it might be a promising prognostic biomarker for ESCA." (PMID 35003212, 2021). "HNRNPA2B1 upregulates ACLY and ACC1 gene expression during fatty acid metabolism to promote esophageal cancer (ESCA) progression, while the knockdown of HNRNPA2B1 suppresses the growth, metastasis and invasion of tumor cells." (PMID 37055798, 2023). "In our previous study on oesophageal cancer (ESCA), the m6A reader HNRNPA2B1 upregulated the expression of ATP citrate lyase (ACLY) and acetyl-CoA carboxylase (ACC1), two fatty acid synthetic enzymes, and promoted ESCA progression and metastasis." (PMID 36632454, 2023). "Finally, HNRNPA2B1 is highly valued in the diagnosis of LUAD, lung squamous cell carcinoma, breast invasive carcinoma, esophageal carcinoma, and liver hepatocellular carcinoma." (PMID 35529270, 2022).
frontotemporal dementia (17 papers, 2014 to 2026). Frontotemporal dementia (FTD) comprises a group of neurodegenerative disorders, characterized by progressive changes in behavior, executive dysfunction and language impairment, as a result of degeneration of the medial prefrontal and frontoinsular cortices. "Interestingly, hnRNPA2B1 is involved in RNA trafficking in neurons, and mutations in hnRNPA2B1 cause a multisystem proteinopathy called inclusion body myopathy with Paget disease and frontotemporal dementia." (PMID 27065789, 2016). "Variants in hnRNPA2B1 are associated with inclusion body myopathy with early-onset Paget disease with or without frontotemporal dementia, but have been described in ALS." (PMID 36515702, 2023). "Furthermore, hnRNPA2B1 interacts with another RNA-binding protein, TDP-43, whose presence in protein inclusions is a hallmark of ALS and frontotemporal dementia, and with PPIA, a biomarker of ALS and a key regulator of TDP-43 function." (PMID 27065789, 2016). "Thus, MATR3 is among the family of genes including VCP, HNRNPA1, HNRNPA2B1 and SQSTM1 that cause “multisystem proteinopathy” associated with either one or a combination of ALS/frontotemporal dementia (FTD), VCPDM and Paget’s disease of bone." (PMID 32811564, 2020).
gastric cancer (17 papers, 2016 to 2026). A primary or metastatic malignant neoplasm involving the stomach. "Besides that, H. pylori infection not only induced activation of the NF-κB signaling pathway, but also recruited NF-κB to the promoter region of the hnRNPA2B1 gene and caused its upregulation in gastric cancer cells." (PMID 40051725, 2025). "In gastric cancer, hnRNPA2B1 stabilizes lncRNA NEAT1, facilitating CSC properties and chemoresistance via Wnt/β-catenin activation." (PMID 41522354, 2026). "In gastric cancer, global dysregulation of the m6A machinery has also been documented, with METTL3, FTO, YTHDFs, IGF2BPs and hnRNPA2B1 frequently upregulated in patient tissues and associated with poor prognosis, advanced stages and metastasis." (PMID 41228380, 2025). "In gastric cancer, the high expression of hnRNPA2B1 is closely related to poor prognosis in patients, mediating the process of malignant transformation such as gastric cancer migration and invasion." (PMID 40051725, 2025). "Overall, H. pylori infection tends to push the progression of gastric cancer into a more aggressive phase by initiating NF-κB signaling pathway and promoting the expression of hnRNPA2B1." (PMID 40051725, 2025). "While hnRNPA2B1 can lower the glycolytic metabolism in gastric cancer cells, inhibit tumor growth and reduce liver metastasis, it also makes these cells more sensitive to the chemotherapy drug cisplatin (CDDP)." (PMID 40051725, 2025). "hnRNPA2B1 promotes gastric cancer development and chemotherapy resistance partially through increasing the expression of BIRC5-202 transcript, which provide new treating opportunity for chemo-resistant patients." (PMID 34044823, 2021). "In addition, other studies have shown that HNRNPA2B1 can promote the progression of oral squamous cell carcinoma and gastric cancer." (PMID 37072750, 2023). "The aberrant level of HNRNPA2B1 has been shown in colon and gastric cancers." (PMID 33094859, 2021). "This means that hnRNPA2B1 might play dule roles in the intricate web of gastric cancer regulation." (PMID 40051725, 2025). "From the molecular biology perspective, growing evidence shows that H. pylori probably induce the expression of NF-κB, miR-204, miR-27a, hnRNPA2B1, and JARID1B, which play crucial roles in the progression of CAG into gastric cancer." (PMID 40051725, 2025). "The m6A RNA modifications and their regulators—including METTL3, ALKBH5, FTO, YTHDFs, hnRNPA2B1, and IGF2BP2—have particularly emerged as key drivers of chemotherapy resistance in gastric cancer." (PMID 41228380, 2025). "TCF7L2 can promote gastric cancer metastasis by regulating PLAUR and forming a MIR100HG/hnRNPA2B1/TCF7L2 axis to promote CRC metastasis." (PMID 38818308, 2024). "Hnrnpa2b1 regulates the alternative splicing of BIRC5 and promotes the progression of gastric cancer." (PMID 35252219, 2021). "Subsequently, the overexpression of hnRNPA2B1 increased its interaction with PABPC1-eIF4F complex and led to following regulation of protein synthesis, promotion of mRNA levels and malignant progression in gastric cancer." (PMID 40051725, 2025). "The lncRNA NEAT1, in conjunction with hnRNPA2B1, targets RPRD1B mRNA stability, activating the c-Jun/c-Fos/SREBP1 axis to promote fatty acid metabolism and primary tumor lymph node implantation in gastric cancer (GC)." (PMID 37546413, 2023).
multiple myeloma (17 papers, 2017 to 2025). "In the context of multiple myeloma, the expression of the HNRNPA2B1, USP1, RRM1, SPAG5, PCNA and TOP2A genes has been studied." (PMID 37048102, 2023). "For example, hnRNPA2B1 is a potential therapeutic target in multiple myeloma through its mediation of the expression of AKT3." (PMID 37990246, 2023). "In multiple myeloma, HNRNPA2B1 was shown to recognize the m6A site of ILF3 and enhanced the stability of its mRNA transcript to promote cell proliferation." (PMID 37215455, 2023). "These experiments demonstrate that myeloma cells hnRNPA2B1 regulated monocytes IRF8 and NFATc1 or MSCs RUNX2 expression through exosomes miR-92a-2-5p or miR-373-3p." (PMID 36451863, 2022). "To analyze the role of HNRNPA2B1 in myeloma cells, we compared the transcriptome sequencing results for MM cells transfected with sh-HNRNPA2B1-8226 and the control sh-NC-8226." (PMID 36401285, 2022). "S/BS) and bone formation rate in the mice injected with myeloma cells expressing high levels of hnRNPA2B1 (shCtrl or A2B1) than in those injected with low hnRNPA2B1 myeloma cells (shA2B1 or Vec)." (PMID 36451863, 2022). "Together, these results reveal that myeloma cells express hnRNPA2B1 enhances lytic bone lesions and tumor progression in patients and mice model with myeloma." (PMID 36451863, 2022). "Our clinical studies examining the correlation between the level of myeloma cell hnRNPA2B1 and the number of osteolytic bone lesions in newly diagnosed patients support this conclusion." (PMID 36451863, 2022). "But our data make a compelling case for a role of hnRNPA2B1 in myeloma-induced bone disease and thus encourage evaluating of these inhibitors." (PMID 36451863, 2022). "Our study elucidated that myeloma cells hnRNPA2B1 upregulates exosomes miR-92a-2-5p and miR-373-3p expression, which enhances osteoclastogenesis and inhibits osteoblastogenesis and thus lead to bone destruction." (PMID 36451863, 2022). "The purpose of this study was to investigate the methylation pattern of multiple myeloma and its effect on the expression of HNRNPA2B1 and downstream targets." (PMID 36401285, 2022). "Based on these results, hnRNPA2B1 was selected as candidate gene, which is highly likely a proliferation-related and bone lesion-related gene in myeloma." (PMID 36451863, 2022). "Through a combination of in vitro, in vivo, and patient samples study, we reported that hnRNPA2B1 has a unique role in myeloma-induced bone disease." (PMID 36451863, 2022). "To determine the functional role of myeloma expressed hnRNPA2B1 in lytic bone lesions, we injected shA2B1 RPMI8226 cells into mouse femurs and caused fewer lytic lesions than did shCtrl RPMI8226 cells." (PMID 36451863, 2022). "To assess the effect of myeloma cells hnRNPA2B1 on osteoblast formation, we cocultured osteoblast progenitors, MSCs, in osteoblast medium with myeloma cells." (PMID 36451863, 2022). "Despite unveiled facets that HNRNPA2B1 is deregulated in several tumors and facilitates tumor growth, a clear role of HNRNPA2B1 in multiple myeloma (MM) remains elusive." (PMID 33794982, 2021). "Furthermore, clinical studies revealed a highly positive correlation between the level of myeloma cells hnRNPA2B1 and the number of osteolytic bone lesions in myeloma patients." (PMID 36451863, 2022). "In this study we clearly demonstrated that myeloma cells hnRNPA2B1 may be responsible, at least in part, for promoting bone destruction in vivo through myeloma cell exosomes." (PMID 36451863, 2022). "The sharp increase in HNRNPA2B1 expression in MM indicates its potential role in myeloma process." (PMID 36401285, 2022). "In this work, we hypothesized that the hnRNPA2B1 plays a role in the pathogenesis of cancer-induced bone destruction in myeloma." (PMID 36451863, 2022). "Our study also suggests that hnRNPA2B1 may be a therapeutic target for bone disease in patients with myeloma." (PMID 36451863, 2022).
multiple myeloma (continued). "To examine whether myeloma cells hnRNPA2B1 can regulate this balance, we first assessed their effects on osteoclast differentiation." (PMID 36451863, 2022). "To assess the role of myeloma-expressed hnRNPA2B1 in osteoclast-mediated bone resorption in vivo, we examined the levels of mouse serum procollagen type I N-terminal propeptide (PINP), a bone formation marker and C-telopeptide of type I collagen (CTX-1), a bone resorption marker." (PMID 36451863, 2022). "To increase translational value, we also explored whether inhibiting hnRNPA2B1 can improve bortezomib treatment effect in myeloma induced osteolytic bone disease." (PMID 36451863, 2022). "Gene Ontology (GO) enrichment showed that the effect of HNRNPA2B1 in myeloma cells is mainly concentrated in the two processes of biological process and cell composition, and that HNRNPA2B1 participates in the regulation of myeloma cells." (PMID 36401285, 2022). "In addition, we found a strong positive correlation between the levels of miR-92a-2-5p or miR-373-3p with hnRNPA2B1 mRNA in patient myeloma cells." (PMID 36451863, 2022). "We immunoprecipitated myeloma cells lysates with an anti-DGCR8 antibody and observed the presence of hnRNPA2B1 proteins in the lysates." (PMID 36451863, 2022). "hnRNPA2B1 and CD138 (myeloma cells surface marker) expression were higher in myeloma cells from patient with high bone lesion numbers (P1) than in those from patient with low lesion numbers (P2)." (PMID 36451863, 2022). "HNRNPA2B1 increased the stabilization of ILF3 mRNA through m6A modification, which in turn increased AKT3 expression to promote multiple myeloma progression." (PMID 36271283, 2022). "Similar to myeloma cells, exosomes isolated from MCF7 cells expressing high levels of hnRNPA2B1 (shCtrl, A2B1) induced more TRAP+ cells formation and less mature osteoblasts than those with low levels of hnRNPA2B1 (Vec or shA2B1)." (PMID 36451863, 2022). "Paired differential analysis identified three of them (hnRNPA2B1, YTHDF3 and hnRNPC) are significantly upregulated in plasma cells of myeloma patients compared to normal plasma cells (Fold Change > 2)." (PMID 36451863, 2022). "Using immunofluorescent staining, we observed a co-localization of hnRNPA2B1 and DGCR8 in myeloma cells." (PMID 36451863, 2022). "Western blot results also showed that hnRNPA2B1 was expressed in most of the bone marrow aspirates of primary myeloma cells and in most of the established human myeloma cell lines, but not in aspirates of plasma cells from normal subjects." (PMID 36451863, 2022). "Because there is no hnRNPA2B1 inhibitor in commercial, the therapeutic effect of these drugs in myeloma-induced bone lesions remains unknown." (PMID 36451863, 2022).
glioblastoma (16 papers, 2017 to 2025). The most malignant astrocytic tumor (WHO grade IV). "HnRNPA2B1 is a crucial member of the hnRNP family, and is correlated with tumorigenesis and the progression of breast cancer, pancreatic cancer, and glioblastoma." (PMID 34277403, 2021). "HnRNPA2B1 also possesses pro-oncogenic functions in glioblastoma, and low expression of hnRNPA2B1 predicts a better prognosis in patients with glioblastoma." (PMID 34277403, 2021). "HNRNPA2B1 has been shown to regulate alternative splicing of tumor suppressors and oncogenes in glioblastoma cell lines." (PMID 33273988, 2020). "PREX1 and ABHD2 have also shown to promote tumor invasion and progression in glioblastoma, while the tumor suppressor BIN1 was found to be regulated by HNRNPA2B1, a putative proto-oncogene in GBM." (PMID 32070274, 2020). "Driver mutations have been found in several RNA-binding proteins (e.g., SF3B1, U2AF1, SRSF2, HNRNPA2B1, SRRM2) in cancers ranging from blood malignancies to glioblastoma, but several questions remain regarding how widely this group of proteins and their targets are involved in cancer." (PMID 35581644, 2022). "Heterogeneous nuclear ribonucleoprotein A2B1 (HNRNPA2B1) and heterogeneous nuclear ribonucleoprotein C (HNRNPC) as the members of heterogeneous nuclear ribonucleoprotein family, have been found to be up-regulated in various types of cancers, such as liver cancer and glioblastoma." (PMID 36536402, 2022).
liver cancer (16 papers, 2017 to 2024). An epithelial or non-epithelial malignant neoplasm that arises from the liver. "We also analyzed TCGA database and found upregulated expression of hnRNPA2B1 in some malignancies including breast, colon, lung and liver cancer." (PMID 36451863, 2022). "Studies have shown that HNRNPA2B1, as an m6A reader, mediates alternative splicing of target RNA and enhances primary miRNA processing, which is highly expressed in liver cancer." (PMID 36462500, 2022). "A previous study found that HNRNPA2B1 promoted the NF-κB signaling pathway to facilitate tumor metastasis in liver cancer." (PMID 32552682, 2020). "hnRNPA2B1 plays an important role in the accumulation of HIF-1α in Hep3B liver cancer cells under mimetic hypoxia." (PMID 30755586, 2019). "These previous data, along with the data in the current study, indicate that the down-regulation of hnRNPA2B1 plays an important role in TSA-induced liver cancer cell death through the induction of p21 expression and deactivation of AKT." (PMID 28993733, 2017). "The current study is the first to provide direct evidence that by interacting with hnRNPA2B1, TSA-induced uc002mbe. deactivates AKT, increases p21 and has a cytostatic effect in human liver cancer cells in vitro and in vivo." (PMID 28993733, 2017). "Therefore, the interaction of uc002mbe. and hnRNPA2B1 in mediating AKT deactivation and p21 induction is involved in the cytostatic effect of trichostatin in liver cancer cells." (PMID 28993733, 2017). "Thus, the interaction of uc002mbe. and hnRNPA2B1 in mediating AKT deactivation and p21 induction is involved in the cytostatic effect of trichostatin in liver cancer cells." (PMID 28993733, 2017). "In addition, upregulation of typical splicing proteins such as SRSF2, hnRNPL, hnRNPA2, hnRNPA2B1 and hnRNPAB were previously observed in liver cancers 33-37, although their misregulated splicing events have not been fully identified." (PMID 32483414, 2020).